MIR100 (microRNA 100)
Synonyms: hsa-mir-100; MIRN100; miR-100
Gene: MicroRNA gene on chromosome 11 (122,152,229 to 122,152,308, reverse strand). Ensembl gene ENSG00000207994.
Gene Ontology:
Biological process: miRNA-mediated post-transcriptional gene silencing
Cellular component: RISC complex
Homologues: Orthologues: chimpanzee ptr-mir-100 (100% identical), macaque mml-mir-100 (98% identical), guinea pig MIR100 (90% identical), mouse Mir100 (90% identical), rat Mir100 (89% identical), pig ssc-mir-100 (84% identical), zebrafish mir100-1 (84% identical), zebrafish mir100-2 (79% identical), dog MIR100 (65% identical). Paralogues in human: MIR99A (76% identical), MIR99B (58% identical), MIR10A (51% identical), MIR125B2 (50% identical), MIR125A (46% identical), MIR125B1 (42% identical), MIR10B (40% identical).
Diseases named in the same sentence as MIR100 in open-access papers:
MIR100 is named in the same sentence as 10 diseases in open-access papers, as found by Europe PMC text mining. Sharing a sentence is not in itself a finding about the gene and the disease. The quoted sentences say what the papers report.
breast cancer (3 papers, 2018 to 2025). A primary or metastatic malignant neoplasm involving the breast. "Our previous study has demonstrated that microRNA100 (Mir100) has a pivotal role in inhibiting breast cancer initiation and progression." (PMID 30446635, 2018). "Furthermore, a wide range of miRNAs has been related to breast cancer, either acting as tumor suppressors (e.g., MIR100, MIR1-1, or MIR114) or oncogenes (e.g., MIR115, MIR17, or MIR224)." (PMID 39125744, 2024).
autism (1 paper, 2020). Persistent deficits in social interaction and communication and interaction as well as a markedly restricted repertoire of activity and interest as well as repetitive patterns of behavior. "Finally, Mir100 (paired with cadherin Cdh9), is associated with neurological disorders such as AD, schizophrenia and autism." (PMID 32093602, 2020).
colon cancer (1 paper, 2016). "The rs1834306 A allele in MIR100, which determines progression time in colon cancer, appeared linked to both infertility (p=0.040) and advanced endometriosis stage (p=0.041)." (PMID 27741504, 2016).
endometriosis (1 paper, 2016). The growth of functional endometrial tissue in anatomic sites outside the uterine body. "Genetic variants in MIR196A2 (rs11614913) and MIR100 (rs1834306) were found to be associated with endometriosis development and related clinical phenotypes, such as infertility and pain." (PMID 27741504, 2016). "Our data indicate that genetic variations at rs1834306 in MIR100 (p=3.5×10−3, OR: 1.64; 95% CI: 1.24–2.17) and rs11614913 in MIR196A2 (p=3.5×10−3, OR: 1.65; 95% CI: 1.24–2.19) are associated with endometriosis risk." (PMID 27741504, 2016).
MIR100 also shares sentences with these, for which no sentence is quoted: bacterial infection (1 paper); cancer (1); Infertility (1); neurological disorders (1); schizophrenia (1); tumor (1).